ENSG00000277922
Gene: Miscellaneous RNA gene on chromosome X (74,293,357 to 74,293,574, forward strand). Ensembl gene ENSG00000277922.
Gene Ontology:
Biological process: positive regulation of gene expression